RNU6-342P (RNA, U6 small nuclear 342, pseudogene)
Gene: Small nuclear RNA gene on chromosome 3 (27,265,580 to 27,265,683, reverse strand). Ensembl gene ENSG00000207251.
Homologues: Orthologues: chimpanzee U6 (98% identical), macaque U6 (88% identical), pig U6 (85% identical), dog U6 (78% identical), dog U6 (76% identical), mouse Gm22013 (72% identical), rat LOC120097967 (68% identical). Paralogues in human: RNU6-1316P (87% identical), RNU6-211P (87% identical), RNU6-1031P (86% identical), RNU6-20P (86% identical), RNU6-214P (86% identical), RNU6-35P (86% identical), RNU6-434P (86% identical), RNU6-574P (86% identical), RNU6-1036P (85% identical), RNU6-1145P (85% identical), RNU6-1152P (85% identical), RNU6-128P (85% identical), and 1286 more.